MYD88 (MYD88 innate immune signal transduction adaptor)
Diseases named in the same sentence as MYD88 in open-access papers (continued):
Sharing a sentence is not in itself a finding about the gene and the disease.
tumor (continued). "Consequently, MyD88 activates TLR4 signaling, leading to the expression of anti-apoptotic proteins, and increased pro-tumor inflammation." (PMID 40560045, 2025). "HMGB1, released by dying tumor cells, may be recognized by DCs in a Toll-like receptor 4 (TLR4)- and myeloid differentiation primary response gene 88 (MyD88)-dependent manner, leading to a potent immune response." (PMID 39857785, 2025). "UA activates the natural immune system through the TLR‐2‐myeloid differentiation primary response 88 (MyD88)–TRAF6 pathway, while PD‐L1 blockade promotes cytotoxic T cell infiltration, leading to significant tumor regression by simultaneously engaging innate and adaptive immunity." (PMID 40060195, 2025). "Significantly, our findings indicate that the impact of MyD88 is not confined to immune responses but also permeates into the metabolic processes of the tumor." (PMID 39744584, 2025). "CD8α:MyD88 T cells exhibited enhanced proliferation, cytokine production (IFN-γ, TNF-α), elevate cytotoxic activity, and increased costimulatory receptor expression, leading to tumor regression in a B16-F1 melanoma model." (PMID 40948803, 2025). "The suppression of MyD88 and downstream mediators like p-ERK and p-NF-kB by SsnB suggests a potent anti-inflammatory effect, which could disrupt the tumor-supportive inflammatory milieu." (PMID 40143078, 2025). "The MyD88/CD40 signaling modules, whether inducible or constitutive, significantly improve the survival, persistence, and anti-tumor activity of CAR T-cells by driving the activation of NF-κB and MAPK." (PMID 39941106, 2025). "Furthermore, downregulating LINC00886 reduces the expression of TLR4, Myd88, phosphorylated NF-κB p65, and PD-L1, while increasing TNF-α and IFN-γ levels and enhancing CD8 + T cell antitumor activity, thereby reducing tumor cell immune escape." (PMID 40999508, 2025). "In contrast, tumors from MyD88-/- animals treated with BCG do not show an increase in the inflammatory infiltrate and induces an M2-like tumor-associated macrophages profile, indicating a “cold” pattern of the TME (protumoral) favoring tumor growth." (PMID 38835781, 2024). "Our results showed a significant increase in levels of expression of inflammatory cytokine IL-1 β (p < 0.01), IL-6 (p < 0.001), TNF-α (p < 0.001), and other related genes including TRAF6 (p < 0.01), MYD88 (p < 0.01), and GDF-15 (p = 0.005) in tumor-bearing mice compared to controls." (PMID 39394174, 2024). "The pro-tumorigenic effect of commensal bacteria likely depends on their activation of the TLRs pathway in bone marrow cells, as chimeric mouse analysis showed that the absence of Myd88 in bone marrow donors inhibited tumor growth." (PMID 38523155, 2024). "Moreover, Helicobacter pylori infection stimulates Toll-like receptor (TLR)/MyD88 and COX-2/PGE2 pathways, resulting in NF-κB activation with different inflammatory responses in tumor tissues." (PMID 39057074, 2024). "Moreover, Helicobacter pylori infection stimulates the TLRs/MyD88 and COX-2/PGE2 pathways, leading to the activation of NF-κB and subsequent induction of an inflammatory response in tumor tissues." (PMID 39057074, 2024). "Anti-tumor effect of MIP through the TLR2-MyD88 axis has been well elucidated whereas the TLR9- MyD88 axis has not been studied yet." (PMID 37122749, 2023). "It is well known that Myd88 is a central node of inflammatory pathways, which links the IL-1/TLR and Ras oncogenic signaling pathways for the induction of proinflammatory cytokines and the maintenance of tumor cell viability." (PMID 37968706, 2023). "The study confirmed that in nATF6IEC MyD88/TRIF-knockout mice, the bacterial entry in the gastrointestinal tract’s mucus layer induced (MYD88)/TLR adaptor molecule 1 (TRIF)-dependent Stat3 signalling, which led to the tumor promotion." (PMID 37361202, 2023).
tumor (continued). "TLR/MyD88 signaling pathway is proved to play an essential role in MDSC‐mediated immune escape in CAC development and is a promising focus for revealing the mechanisms of MDSC that facilitate immunosuppression and tumor progression." (PMID 38140790, 2023). "Therefore, lnc-MyD88 and AFP can also be used as effective tumor markers to distinguish HCC from LC, and the AUC value of lnc-MyD88 suggested that lnc-MyD88 had better diagnostic efficiency than AFP in the process of distinguishing HCC from LC." (PMID 36793272, 2023). "F. nucleatum lipopolysaccharide leads to strong induction of the TLR4/MYD88 innate immune signaling pathway to regulate miRNA expression, and the expression of specific miRNAs can promote tumor proliferation and the development of chemoresistance through the TLR4/MYD88 pathway." (PMID 35198889, 2022). "These inducible MyD88/CD40 CAR T cells exhibited superior T-cell proliferation, cytokine production, and tumor killing ability compared to second-generation CAR T cells that did not contain the inducible MyD88/CD40 molecule." (PMID 35628381, 2022). "Therefore, if IGH-BCL2 translocation, MYD88 L265P mutation, and BRAF V600E mutation were also detected and the results were combined with the model, the overall predictive sensitivity could increase to 0.88, and was markedly improved in samples with low tumor cell content." (PMID 34802044, 2022). "Therefore, MDSC elimination by blocking the action of myeloid differentiation factor 88 (MyD88), which is a key adaptor-signaling molecule that affects TLR activity, seems to be an ideal tumor immunotherapy." (PMID 35089465, 2022). "Similarly, anthracyclines and oxaliplatin can induce tumor cell death via the release of HMGB1, which is recognized by TLR4 expressed on DCs and subsequently activates MyD88, resulting in type I IFN production." (PMID 35292881, 2022). "One explanation could be that low or high activation levels of TLR4/MyD88 signaling lead to significantly different expression levels of specific TLR4/MyD88 target genes, which in turn would affect the tumor infiltration capacity in opposing ways." (PMID 36224342, 2022). "Although the absence of MyD88 in the brain parenchyma led to reduced infiltration by tumor cells, it also reduced MG and AS activation in the organotypic brain-slice ex vivo co-cultures and in the short-term in vivo experiment." (PMID 36224342, 2022). "The expression of constitutively active MYD88 mutants, DD or L265P, but not WT MYD88, resulted in the efficient induction of tumour growth." (PMID 33597599, 2021). "Also, deletions of JAK2, CD274 and MYD88 genes, and amplification of FGFR4 and NPM1 genes, are also involved in clinical trials for other tumor types." (PMID 33668731, 2021). "Altogether, the Myd88L252P tumor signature highlights proliferation as well as canonical NF-κB p65/RelA activation (but not RelB), which is in agreement with the known fact that MYD88 activates the classical NF-κB pathway." (PMID 34017329, 2021). "The result showed that treatment with PcrV-primed WT BMDMs, but not TLR4−/− or MyD88−/− BMDMs, decreased tumor growth and weight." (PMID 34900687, 2021). "Assessing multiple biomarkers such as TLR4, MyD88 and MAD2 which give greater insight into the pathological makeup of a patient’s tumour may help to direct therapies and more suitable treatment combinations in order to improve overall outcome." (PMID 33370338, 2020). "In consistence with these findings, T-cell proliferation is inhibited by MDSCs isolated from mice treated with tumor derived-exosomes but not by MDSCs isolated from MyD88 knockout mice treated with tumor derived-exosomes." (PMID 32793192, 2020). "MyD88 knockout MDSCs failed to induce suppression in tumor-bearing mice, which resulted in an immunogenic response, followed by a significant reduction in tumor mass." (PMID 32932705, 2020).
tumor (continued). "Of note, they demonstrated an additional mechanism of action of TLR2 activation, which was based on the TLR2/MyD88-mediated activation of the Wnt pathway, with the induction of the expression of its targets CD44 and Lgr5, which may lead to tumor initiation." (PMID 33321934, 2020). "MyD88 expression was significantly higher in tumor tissue than that in non-malignant gastric cardia tissues (p = 0.025)." (PMID 32477927, 2020). "The silkworm peptide could play role in inhibiting tumor growth, and it may be related to TLR2‐induced MyD88‐dependent pathway in vitro." (PMID 31024698, 2019). "In this study, we explored the role of MyD88 and TLRs in MIP-induced tumor regression." (PMID 31590685, 2019). "It was observed that MIP therapy resulted in significant tumor regression in wild-type, but not in MyD88−/− mice." (PMID 31590685, 2019). "In stark contrast, this pattern was absent (Myd88, Cd4, Tlr9, Ly96) in tumor-bearing and/or –resected mice or reversed, in one case (C3)." (PMID 31019214, 2019). "Despite relatively high variability in tumor burden in the PBS group, significant antitumor activity was observed with the GalNAc-conjugated MyD88 ASO, with 10 of 16 animals being tumor free compared to the PBS group where only two animals had no tumors (p < 0.05)." (PMID 31303442, 2019). "Another recent study has also shown that the loss of the Hippo pathway kinases large tumour suppressor 1 and 2 (LATS1/2) in tumour cells inhibits tumour growth by nucleic-acid-rich-EVs, which induce a type I interferon response (IFN) via the Toll-like receptors-MYD88/TRIF pathway." (PMID 29158316, 2018). "Tumour tissues of mice lacking MyD88 showed lower expression of the Cox2 gene that is involved in inflammation, indicating a role of this gene in reduced tumour formation." (PMID 30348892, 2018). "Firstly, to explore whether Lnc-Myd88 interrelated with HCC, we detected its expression in tumor tissues and corresponding adjacent normal liver tissues." (PMID 29022910, 2017). "On the contrary, the mRNA and protein expressions of TRAM had no remarkable differences among the groups of the MyD88+/+ tumor-bearing mice." (PMID 28303957, 2017). "The mRNA and protein expressions of TRAF-6, NF-κB and AP-1 in the splenocytes of MyD88−/− tumor-bearing mice were not provoked by APS." (PMID 28303957, 2017). "The concentrations of TNF-α and IL-6 in the APS group had no obvious difference from those in the NS group of the MyD88−/− tumor-bearing mice (P > 0.05)." (PMID 28303957, 2017). "In the ApcMin/+ mouse model of intestinal tumorigenesis, activation of the MyD88 pathway is related to stabilization of c-Myc protein but not to up-regulation of its mRNA in epithelial cells, resulting in a decrease in tumor growth in ApcMin/+Myd88−/− mice." (PMID 29041928, 2017). "In addition, the secretion of cytokines after treatment with APS in the MyD88−/− mice were significantly reduced, compared with those in the APS groups of the MyD88+/+ tumor-bearing mice (P < 0.05)." (PMID 28303957, 2017). "We found that MyD88-downregulated B16 cells exhibited significantly impaired tumor growth compared with SCR control cells or non-transduced B16 cells." (PMID 28662055, 2017). "In this work, we demonstrate that silencing MyD88 in B16 cells, do not alter their proliferation/survival capacity in vitro but it inhibits tumor growth in vivo." (PMID 28662055, 2017). "In vitro, however, the absence of MyD88 in CD8+ T cells results in defective cytotoxic activity against tumor tissue and a reduced secretion of pro-inflammatory cytokines to host antigens." (PMID 27529218, 2016). "MyD88 was required for robust, SREC-I mediated immune responses to tumor antigens." (PMID 25836976, 2015). "BM chimeras lacking MyD88 in the haematopoietic compartment exhibited a striking protection against wound-induced tumour formation." (PMID 25575023, 2015).
tumor (continued). "The fact that CARMA1-KO but not MyD88-KO mice fail to reject MC57-SIY tumors suggest that TCR-NF-κB but not TLR-NF-κB plays a role in tumor control." (PMID 25648675, 2015). "Selected malignant patient tumour samples were divided into two groups based on previous IHC results (MyD88 positive, n = 10; MyD88 negative, n = 12)." (PMID 24977712, 2014). "The median OS time for patients with MyD88 positive EOC was 28 months (n = 21), while patients with MyD88 negative tumours (n = 12) had significantly longer overall survival (47 months, p = 0.029)." (PMID 24977712, 2014). "The median time to recurrence (from the time of surgery) for patients with MyD88 positive tumours was 16 months, whereas MyD88 negative tumours recurred at a median time of 42 months (p = 0.018)." (PMID 24977712, 2014). "The median OS time for patients with MyD88 positive tumours was 43 months, compared to 108 months for MyD88 negative tumours (p = 0.008)." (PMID 24977712, 2014). "In addition to having tumor-initiating properties, the CD44+/MyD88+ subtype of EOC cells express multiple pluripotency-associated genes, can differentiate into vascular tumor progenitors and, in addition, undergo EMT to yield migratory mesenchymal CSCs." (PMID 24403249, 2013). "The TLR4 and MyD88 expression were evaluated in human EOC cell lines and tumor sections." (PMID 22533866, 2012). "A common immunopathogenic mechanism across many of these cancers is the activation of the MyD88/NF‐κB axis, which drives the secretion of pro‐inflammatory cytokines (e.g., IL‐6, TNF‐α), promotes angiogenesis, and upregulates anti‐apoptotic genes, thereby creating a tumor‐supportive microenvironment." (PMID 40922674, 2025). "The absence of MyD88 in knockout models prevented TI-mediated inflammatory cell recruitment within the tumor microenvironment, consequently impairing tumor suppression and T cell-derived INF-γ production, collectively establishing the essential role of the MyD88 pathway in BCG’s anti-tumor immunity." (PMID 41403926, 2025). "Sequencing of tumor tissues from 22 patients showed that MYD88 mutations were the most frequent genetic alterations, two patients with CARD11 mutation did not respond to treatment and three patients without an MYD88 or CD79B had response after treatment." (PMID 40475774, 2025). "Inflammatory cytokines TNF-α, IL-12 and IFNγ were increased especially in cell cultures with spleen cells from WT mice treated in vitro with BCG, but not with spleen cells from MyD88-/-, reinforcing the importance of MyD88 to induce cell death mechanisms and tumor control." (PMID 38835781, 2024). "The adaptor molecule MyD88 probably acts as a bridge between the innate and the adaptive immunity, by promoting the activation of antigen presenting cells and consequently priming lymphocytes that exhibit IFN-γ secretion and cytotoxicity profile against tumor cells." (PMID 38835781, 2024). "However, there is no comprehensive scoping review about MyD88 on the interplay between tumor microenvironment as well as immune escape." (PMID 38785969, 2024). "In this regard, the in vitro data suggest that the free bacteria or the infected tumor cells present into the TME are capable to stimulate the activation of macrophages and the release of cytokines and chemokines (TNF-α, IL-6, IL-12, and CXCL10) in a MyD88-dependent manner." (PMID 38835781, 2024). "While MyD88 is renowned for the role in recognizing and responding to microbial pathogens in innate immunity, it also plays a pivotal role in numerous non-immune processes, particularly within the context of tumor development." (PMID 38347830, 2024). "Additionally, a recent study found that TJM-2010-2, a novel MyD88 inhibitor, reduced the expression of iNOS, Arg-1, and the immunosuppressive molecule Indoleamine-2,3-Dioxygenase (IDO) by inhibiting MyD88, thus weakening tumor immune escape." (PMID 38785969, 2024).
tumor (continued). "Moreover, despite being a target of TLR8 agonism, we did not see an increase in TLR8 signaling molecules (except MYD88 in dendritic cell populations) in post-treatment biopsies, possibly because of tumor resection timing (scRNAseq)." (PMID 39697344, 2024). "Interestingly, the r3LCMV therapy was still effective in tumor-bearing MyD88–/– mice, demonstrating that MyD88 was not required for the antitumoral effect." (PMID 38861331, 2024). "Consequently, the increased expression of these cytokines by tumor cells could signal to immune cells or have an intrinsic effect on tumor cells, therefore explaining the observed effect of TLR/IKKβ/MyD88 knockout on naïve tumorigenesis." (PMID 37283745, 2023). "Indeed, OAd-MSC MyD88−/− also showed higher tumor homing than OAd-MSC WT, while no remarkable differences were observed in the biodistribution to other organs." (PMID 36875156, 2023). "The discovery of the role of the circCUL2/MyD88/NF-κb signaling pathway in activating and maintaining iCAFs in the TME may be needed for the development of rational strategies that selectively target tumor-promoting CAFs in PDAC." (PMID 35189958, 2022). "Finally, we confirm the importance of MyD88 in macrophages showing that BCG induces the release of inflammatory cytokines (TNF-α, IL-6, IL-1β) and nitric oxide by WT macrophages in co-culture with infected tumor cells, but not in MyD88−/− BMDMs." (PMID 34341449, 2021). "Additionally, BCG intratumoral treatment regulates cellular infiltrate in TME with an increase of inflammatory macrophages, neutrophils and CD8+ T lymphocytes, suggesting an immune response activation that favors tumor remission in WT mice but not in MyD88−/−." (PMID 34341449, 2021). "The lack of MyD88 molecule completely eliminated the effect of BCG in tumor volume reduction." (PMID 34341449, 2021). "The MyD88-dependent TLR2 signaling activates NF-κB pathway, which in turn stimulates the transcription of proinflammatory cytokines and chemokines, and may lead to cellular proliferation and tumor progression." (PMID 34715891, 2021). "Taken together, these data demonstrate high expression of CXCR4 in WM cells harboring the MYD88 L265P cases independent of the CXCR4 mutational status and show high expression of genes associated with CXCR4 signaling and tumor growth particularly in CXCR4Mut cases." (PMID 33669329, 2021). "However, in our model, loss of downstream IL-1 signaling mediators, such as MYD88 and RELA, did not affect the tumor-promoting function of the enteric glia." (PMID 33282743, 2020). "However, the roles of MyD88 and STING may be dependent on the micromilieu, since the majority of models provide evidence for potent anti-tumor effects of MyD88 and STING." (PMID 32674488, 2020). "WNT5A has dual effects on the tumor microenvironment; it can promote inflammation and chemotaxis of immune cells through activation of the ROR1/Akt/P65 pathway, as well as stimulating the TLR/MyD88/p50 pathway in myelomonocytic cells, to promote synthesis of the anti-inflammatory cytokine, IL-10." (PMID 33034614, 2020). "One possible mechanism of MYD88/CD79B-derived lymphomagenesis involves TLR/MYD88 signaling, which might initiate tumor growth in IP sites, characterized by their favorable microenvironments, whereas concomitant CD79B mutations could further promote lymphomagenesis by enhancing the BCR signaling." (PMID 33050534, 2020). "Similarly, β-lap treatment increased the level of IFNβ in the tumor tissue in WT but not in Myd88−/− mice." (PMID 31324798, 2019). "Likewise, in EG7 lymphoma, B16, and inducible BrafV600EPTEN melanoma models exogenous IL-33 activated myeloid DCs within the tumor microenvironment increasing antigen cross-presentation and restoring anti-tumor T cell activity in a ST2, MyD88, and STAT1-dependent manner." (PMID 30483263, 2018).